GGTA2P (glycoprotein alpha-galactosyltransferase 2, pseudogene)
Synonyms: HGT2; GGTA1P; GLYT2L; GLYT3
Gene: Processed pseudogene on chromosome 12 (67,265,842 to 67,266,966, reverse strand). Ensembl gene ENSG00000237766.
Diseases named in the same sentence as GGTA2P in open-access papers:
GGTA2P is named in the same sentence as 2 diseases in open-access papers, as found by Europe PMC text mining. Sharing a sentence is not in itself a finding about the gene and the disease.
GGTA2P shares sentences with these, for which no sentence is quoted: candidosis (1 paper); infection (1).